CRNN (cornulin)
Description:
Promotes cell proliferation, G1/S cell cycle progression and induces expression of the cell cycle regulator CCND1. Regulates proliferation induced by pro-inflammatory cytokine response via activation of NFKB1 and PI3K/AKT signaling pathways.
Synonyms: C1orf10; PDRC1; SEP53
Tractability: No criterion of Open Targets' tractability assessment is met for any kind of drug.
Gene: Protein-coding gene on chromosome 1 (152,409,243 to 152,414,263, reverse strand). Ensembl gene ENSG00000143536.
Subcellular location: Cytoplasm
Gene Ontology:
Molecular function: protein binding; calcium ion binding; calcium-dependent protein binding; transition metal ion binding
Biological process: cell-cell adhesion; keratinocyte activation; response to heat; regulation of phosphatidylinositol 3-kinase/protein kinase B signal transduction
Cellular component: cytoplasm; extracellular exosome; membrane
Genetic constraint (gnomAD): Loss-of-function variants: 39 observed, 45.84 expected, observed/expected ratio (o/e) 0.85, 90% interval 0.66 to 1.11. The upper end of that interval is the gene's LOEUF score, 1.11, which puts it in group 4 of 6, group 1 being the genes least tolerant of losing a copy. Missense variants: 606 observed, 633.67 expected, observed/expected ratio (o/e) 0.96, 90% interval 0.89 to 1.02. Synonymous variants: 240 observed, 242.27 expected, observed/expected ratio (o/e) 0.99, 90% interval 0.89 to 1.1.
Homologues: Orthologues: chimpanzee CRNN (99% identical), macaque CRNN (90% identical), pig CRNN (67% identical), rabbit CRNN (60% identical), dog CRNN (60% identical), rat Crnn (56% identical), mouse Crnn (56% identical), zebrafish s100a10a (6% identical), zebrafish s100s (6% identical), zebrafish s100t (6% identical), tropical clawed frog s100a11 (5% identical). Paralogues in human: S100A8 (6% identical), S100P (6% identical), S100Z (6% identical), S100A1 (6% identical), S100A12 (5% identical), S100A2 (5% identical), S100A9 (5% identical), S100A3 (5% identical), S100A4 (5% identical), S100A11 (5% identical), S100A6 (5% identical), S100G (5% identical), and 9 more.
Diseases named in the same sentence as CRNN in open-access papers:
CRNN is named in the same sentence as 43 diseases in open-access papers, as found by Europe PMC text mining. Sharing a sentence is not in itself a finding about the gene and the disease. The quoted sentences say what the papers report.
esophageal squamous cell carcinoma (7 papers, 2013 to 2024). Esophageal squamous cell carcinoma (ESCC) is a type of esophageal carcinoma (EC) that can affect any part of the esophagus, but is usually located in the upper or middle third. "Loss of CRNN expression has been correlated with an advanced tumor length, a greater tumor invasion depth, lymph node metastasis, and poor survival in patients with esophageal squamous cell carcinoma." (PMID 29868478, 2018). "Transfection of esophageal squamous cell carcinoma (ESCC) cell lines to overexpress Cornulin leads to decreased viability, proliferation, and foci-formation ability in these malignant cells." (PMID 39336714, 2024). "On the other hand, Cornulin overexpression in oral and esophageal squamous cell carcinoma cell lines leads to cell cycle arrest at the G1/S checkpoint and downregulation of cyclin D1 expression, perhaps highlighting its role as tumor suppressor gene product." (PMID 36721574, 2022). "Apart from eczema, earlier studies have demonstrated that CRNN is downregulated in various types of cancers, including esophageal squamous cell carcinoma, oral squamous cell carcinoma, cervical squamous cell carcinoma, head and neck squamous cell carcinoma, and thyroid cancer." (PMID 39292704, 2024). "By using cDNA microarray analysis, we identified cornulin (CRNN) gene was frequently downregulated in esophageal squamous cell carcinoma (ESCC)." (PMID 23894350, 2013). "Studies have documented this downward trend in Cornulin expression in cervical SCC, oral SCC, esophageal SCC, and cutaneous SCC." (PMID 36721574, 2022). "Previous studies have reported that CRNN is downregulated in OSCC and esophageal squamous cell carcinoma." (PMID 34224327, 2021). "Furthermore, inhibition of G1/S checkpoint cell cycle arrest in esophageal squamous cell carcinoma is achieved by upregulating P21WAF1/CIP1 and Rb expression by CRNN." (PMID 39292704, 2024).
squamous cell carcinoma (7 papers, 2022 to 2025). A carcinoma arising from squamous epithelial cells. "Cornulin, encoded by the CRNN gene, has recently gained attention for its potential role in squamous cell carcinomas." (PMID 41465166, 2025). "In recent years, there has been mounting evidence for Cornulin’s association with squamous cell carcinomas of the cervix, esophagus, head and neck, and skin." (PMID 39336714, 2024). "Copious analyses of the molecular changes in squamous cell carcinomas have implicated Cornulin in the pathogenesis and progression of these malignant neoplasms." (PMID 39336714, 2024). "Cornulin expression seems to be downregulated in several squamous cell carcinomas, including cervical, oral, esophageal, and cutaneous squamous cell carcinoma." (PMID 39336714, 2024). "Cornulin, a squamous epithelium-specific protein, has recently garnered attention due to its implications in the progression of squamous cell carcinoma developed in several tissues." (PMID 39336714, 2024). "CRNN, known for its tumor-suppressive functions in cell cycle regulation, is also down-regulated in other squamous cell carcinoma types, suggesting its broader role in epithelial malignancies." (PMID 39596132, 2024). "We have established in an earlier study that Cornulin is less expressed, or even lost, in cutaneous squamous cell carcinoma tissue samples." (PMID 36721574, 2022). "It has been shown that the expression of the epidermal differentiation marker, Cornulin, declines with the progression of squamous cell carcinomas of several tissue types." (PMID 36620799, 2022). "Notably, downregulation of Cornulin has been consistently reported in the squamous cell carcinomas of the cervix, esophagus, and head and neck." (PMID 41465166, 2025). "Recent studies have demonstrated that CRNN are present in various human squamous cell carcinomas." (PMID 39292704, 2024). "The physiologically healthy squamous epithelium displays a considerable level of Cornulin, whereas squamous cell carcinomas have marked downregulation, suggesting that Cornulin expression levels can be utilized for the early detection and follow-up on the progression of these types of cancer." (PMID 39336714, 2024). "Additionally, a comparison of normal gingival keratinocytes with metastatic squamous cell cancer cells represented by the Detroit 562 cell line shows that Cornulin expression was downregulated by 5.2 folds (p = 0.003)." (PMID 36620799, 2022). "Cornulin has been found to be downregulated in various squamous cell carcinomas of other tissues; however, its expression in cSCC has never been studied." (PMID 36561600, 2022). "Therefore, the co-down-regulation of CRNN and KRT4 might synergistically promote the progression of squamous cell carcinomas like HNSCC." (PMID 39596132, 2024).
lung carcinoma (5 papers, 2021 to 2025). "Proteins such as BPIFA, MUC5B, CRNN, and IQGAP warrant further investigation for their potential role in lung cancer screening." (PMID 41573685, 2025). "One study identified twelve proteins, such as members of the annexin family (annexin A1, A2, A3, A5, A6, A11), along with PR-OM1, MUC1, BPIFA1, CRNN, MUC5B and IQGAP, which showed significant differences between lung cancer patients and healthy individuals." (PMID 40575159, 2025).
oral squamous cell carcinoma (5 papers, 2013 to 2024). "Regression analysis showed low expression of Cornulin (p = 0.018), and increased patient’s age (p = 0.008) were predictors of local relapse in oral squamous cell carcinoma, with 34-fold risk and 18-fold risk, respectively." (PMID 34941961, 2021). "This study aims to examine Cornulin expression at the cellular level in various cell lines representative of the successive progression steps of oral squamous cell carcinoma (OSCC), a major type of head and neck cancer." (PMID 36620799, 2022). "Downregulation of CRNN was reported in some cancers, including esophageal cancer, oral squamous cell carcinoma, and head and neck squamous cell carcinoma." (PMID 23894350, 2013). "Low expression of Cornulin is an independent predictor of relapse in oral squamous cell carcinoma." (PMID 34941961, 2021). "The objectives were to evaluate the expression of Ki-67, Cornulin and ISG15 in non-involved mucosal surgical margins and the association of clinicopathological prognosticators with local relapse in oral squamous cell carcinoma." (PMID 34941961, 2021).
cutaneous squamous cell carcinoma (4 papers, 2022 to 2024). "There is about a 2-fold decrease of Cornulin expression in cutaneous squamous cell carcinoma compared to the normal epidermis." (PMID 39336714, 2024). "This study aimed to evaluate the expression of an epidermal differentiation marker, cornulin, in cutaneous squamous cell carcinoma (cSCC)." (PMID 36561600, 2022). "Cornulin has been found to play a role in a common type of skin cancer known as cutaneous squamous cell carcinoma (cSCC), which is one of three major types of malignancies in the skin and is the second most deadly after melanoma and the second most common after basal cell carcinoma." (PMID 39336714, 2024). "Our findings suggest that Cornulin might serve as an indicator for lymph node involvement status in cases of cutaneous squamous cell carcinoma." (PMID 36721574, 2022). "Altogether, Cornulin expression can potentially serve as a valuable prognosticator for cSCC patients as it correlates with metastasis to regional lymph nodes, a key factor in determining the prognosis and recurrence of cutaneous squamous cell carcinoma." (PMID 36721574, 2022).
esophageal cancer (4 papers, 2013 to 2025). A primary or metastatic malignant neoplasm involving the esophagus. "The emerging evidence of Cornulin’s role as a potential diagnostic and prognostic biomarker in esophageal cancer offers promising clinical utility." (PMID 39336714, 2024). "A study has demonstrated that the aberrant expression of squamous epithelial heat shock protein 58 (Cornulin, CRNN) and transgelin 2 (TAGLN2) is associated with the progression of esophageal precancerous lesions to esophageal cancer." (PMID 40018789, 2025). "Altogether, these findings validated previous studies about the role of Cornulin in the development of esophageal cancer." (PMID 39336714, 2024). "Further research and functional studies are warranted to fully understand the roles of TAGLN2 and CRNN in esophageal cancer development and progression." (PMID 37553345, 2023). "In the remaining 11%, slight Cornulin levels were observed in the cytoplasm of early stage ESCC cells, suggesting that Cornulin levels continue to decrease as esophageal cancer progresses." (PMID 39336714, 2024).
cervical cancer (3 papers, 2023 to 2025). A primary or metastatic malignant neoplasm involving the cervix. "The downstream analysis of the functions of CRNN protein would provide a better understanding of the underlying mechanisms in cervical cancer." (PMID 37185759, 2023). "While these studies add credence to the promising diagnostic and prognostic utility of Cornulin, the exact role it plays in cervical cancer tumorigenesis is still largely unknown." (PMID 39336714, 2024). "Cornulin was the only newly identified biomarker with the ability to distinguish among all these three steps in cervical cancer progression." (PMID 39336714, 2024). "Cornulin’s expression patterns in cervical cancer have been examined, and findings support the stepwise downregulation of Cornulin levels that accompanies the progression to neoplasia in the cervix." (PMID 39336714, 2024). "Cornulin was identified among nine differentially expressed genes (DEG) that were characteristic of cervical cancer." (PMID 39336714, 2024). "Moreover, transcriptomics studies seem to be concordant with the proteomics data regarding the downregulation in Cornulin expression as cervical cancer progresses." (PMID 39336714, 2024). "Recent studies have validated Cornulin’s expression patterns in cervical cancer progression using gel-free liquid chromatography coupled mass spectrometry (LC–MS) quantitative analysis of formalin-fixed paraffin-embedded (FFPE) cervical tissues, followed by immunohistochemical detection assays." (PMID 39336714, 2024). "Finally, cornulin may be a potential target for therapeutic interventions in cervical cancer." (PMID 37185759, 2023). "Although annexin A2 and cornulin have been reported in other studies, their expression in cervical cancer FFPE tissues has not been reported." (PMID 37185759, 2023).
oral cancer (3 papers, 2022 to 2024). "Several exploratory proteomics studies have confirmed the correlation between the gradual loss of Cornulin expression and the progression of oral cancer in tissue samples representing the different steps in OSCC carcinogenesis." (PMID 39336714, 2024). "Recent studies have identified salivary Cornulin as a potential biomarker for oral cancer screening." (PMID 39336714, 2024). "Overall, salivary Cornulin consistently and significantly displayed high sensitivity and specificity as a biomarker for oral cancer screening." (PMID 39336714, 2024). "Separately, Cornulin expression significantly correlated with the use of the addictive agent Naswar, a smokeless tobacco product, in oral cancer tissues." (PMID 39336714, 2024). "Specifically, studies have demonstrated that Cornulin has markedly significant downregulation in tissue biopsies from oral cancer patients compared to the normal oral mucosa." (PMID 36620799, 2022). "A liquid chromatography–mass spectrometry proteomic analysis on saliva samples obtained from oral cancer patients and healthy control individuals identified Cornulin among six differentially expressed proteins that can discriminate between the two compared groups." (PMID 39336714, 2024). "Cornulin also proved to be a potential predictor of local relapse, which is a major clinical challenge, with an estimated 20% to 40% of oral cancer patients suffering from a local relapse in the vicinity of the resected tumor despite showing cancer-free surgical margins." (PMID 39336714, 2024). "Follow-up studies to monitor Cornulin levels throughout the clinical course of disease and relative survival rate data are needed to firmly establish this promising biomarker in the clinical setting to supplement current pathological assessment and prognosis for patients afflicted with oral cancer." (PMID 36620799, 2022). "Specifically, salivary Cornulin levels were significantly lower in oral cancer patients compared to non-cancer subjects." (PMID 39336714, 2024).
dysplasia (2 papers, 2023 to 2025). A usually neoplastic transformation of the cell, associated with altered architectural tissue patterns. "In a proteomic analysis evaluating 500 proteins across the OSCC spectrum, Cornulin emerged as the most significantly downregulated protein, demonstrating a consistent stepwise decline in expression from normal mucosa through dysplasia and invasive carcinoma." (PMID 41465166, 2025).
gastric cancer (2 papers, 2015 to 2019). A primary or metastatic malignant neoplasm involving the stomach. "Curiously, gastric cancer showed inverse relationship for CDCA5, CRNN and DUOX1 on prognosis compared to other cancer types (red asterisks)." (PMID 31443700, 2019). "Interestingly, gastric cancer showed inverse relationship for CDCA5, CRNN and DUOX1 on prognosis compared to other cancer types investigated." (PMID 31443700, 2019). "Some nonsynonymous mutations caused low levels of gene activity with down-regulation of mRNA expression (ZNF208, CRNN, IREB2 and ACADL), which may be crucial tumor suppressor genes for gastric cancer and may contribute to the extensive dissemination of cancer cells in abdominal cavity." (PMID 26330360, 2015).
head and neck squamous cell carcinoma (2 papers, 2013 to 2023). A squamous cell carcinoma that arises from any of the following anatomic sites: lip and oral cavity, nasal cavity, paranasal sinuses, pharynx, larynx, and salivary glands. "On the other hand, CRNN expression significantly decreased in tumor tissues of DLBC (Diffuse Large B-Cell Lymphoma), HNSC (Head and Neck Squamous Cell Carcinoma), and ESCA." (PMID 37553345, 2023).
leukoplakia (2 papers, 2020 to 2024). A white patch or plaque on a mucous membrane that cannot be characterized clinically or pathologically as any other disease. "Moreover, Cornulin expression was evaluated in the premalignant leukoplakia lesions in correlation with the severity of dysplasia and the potential for malignant transformation within the leukoplakia lesions." (PMID 39336714, 2024).
psoriasis (2 papers, 2023 to 2024). An autoimmune condition characterized by red, well-delineated plaques with silvery scales that are usually on the extensor surfaces and scalp. "CRNN overexpression was previously shown to aberrantly regulate keratinization by activating the Phosphoinositide 3-Kinase/Akt Pathway, leading to inflammatory diseases, such as psoriasis." (PMID 38375062, 2024). "Cornulin has been studied in inflammatory diseases and may be involved in the pathogenesis of psoriasis." (PMID 37185759, 2023).
tongue squamous cell carcinoma (2 papers, 2021 to 2024). A squamous cell carcinoma that arises from the tongue. "The aim of the study is to identify cornulin (CRNN) protein expression associated with advancement of tongue squamous cell carcinoma (TSCC)." (PMID 33889206, 2021). "Since the tongue is the most common anatomical site for OSCC, a study that focused on the expression of Cornulin in tongue squamous cell carcinoma (TSCC) demonstrated high Cornulin expression in non-malignant oral tissues and a reduced expression in TSCC tissues." (PMID 39336714, 2024).
Ataxia (1 paper, 2023). Ataxia refers to impaired coordination of voluntary muscle movement. "When applying this measure, the ccRNN shows a clear reduction in ataxia-like behaviour compared to cRNN." (PMID 36599827, 2023).
atopic dermatitis (1 paper, 2025). "Examples include defects of filaggrin in atopic dermatitis and the downregulation of cornulin and SPRRs in oesophageal epithelial cancers." (PMID 41319262, 2025).
breast carcinoma (1 paper, 2019). "Low expression of CRNN, CLEC3B and DUOX1 were associated with poor prognosis of breast cancer." (PMID 31443700, 2019).
COVID-19 (1 paper, 2024). A disease caused by infection with severe acute respiratory syndrome coronavirus 2. "COVID-19 severity was associated with immune suppression, overexpression of proinflammatory cytokines, including CRNN, IL1A, S100A7, and IL23A, and activation of pathways involved in keratinocyte proliferation." (PMID 38375062, 2024). "Epithelial cells are directly infected during SARS-CoV-2; thus, CRNN overexpression in our severe COVID-19 cohort may represent a potential pathogenic mechanism employed by SARS-CoV-2 to induce dysregulated inflammatory response via upregulating keratinization at the primary site of infection." (PMID 38375062, 2024). "Taken together, we found that COVID-19 severity in the Ghanaian cohort was associated with dysregulated inflammatory response mediated by MAL, IL1A, IL23A, CRNN, and S100A7 overexpression and suppression of antiviral immune response-related pathways." (PMID 38375062, 2024). "However, in this study, an upregulation of other pro-inflammatory cytokines, including CRNN, IL1A, IL23A, IVL, and S100A7, was associated with severe COVID-19." (PMID 38375062, 2024).
dental caries (1 paper, 2018). The decay of a tooth, in which it becomes softened, discolored, and/or porous. "Fourteen of these age-specific proteins, such as cornulin, myeloblastin, keratin type II cytoskeletal 2 epidermal, keratin type II cytoskeletal 5, and keratin type I cytoskeletal 10, were confirmed to be associated with dental caries." (PMID 30359274, 2018).